PER2 (period circadian regulator 2)
Diseases named in the same sentence as PER2 in open-access papers (continued):
Sharing a sentence is not in itself a finding about the gene and the disease.
bladder cancer (1 paper, 2024). "We identified the circadian rhythm of the clock genes PER2 and BMAL1 and their impact on PPIX accumulation in bladder cancer cell lines UM-UC-3 and J82, as well as in mouse xenograft models." (PMID 39682298, 2024).
bone osteosarcoma (1 paper, 2025). A usually aggressive malignant bone-forming mesenchymal neoplasm arising from the bone. "The transcriptional-level circadian nature of Per2 has been extensively studied and monitored for various applications in vitro, using reporters expressing truncated murine Per2 promoters in NIH3T3 (mouse fibroblast) and U2OS (human bone osteosarcoma) cells, among others." (PMID 41226820, 2025).
breast adenocarcinoma (1 paper, 2015). "Two distinct subpopulations of cells expressing the Per2 protein were observed in both the normal MCF-12A breast epithelial cells and the MDA-MB-231 breast adenocarcinoma cells." (PMID 26347774, 2015).
Cachexia (1 paper, 2014). Severe weight loss, wasting of muscle, loss of appetite, and general debility related to a chronic disease. "We observed reduced amplitudes in the mRNA expression of Reverbα Per2, Pparγ C/ebpα, and associated genes (Fas, Lpl, Scd1, Dgat2) and a parallel increase in Bmal1, Cry1, Pbe and Tfam indicating alterations in the core clock regulation and lipid homeostasis during cachexia." (PMID 24667661, 2014).
cardiac hypertrophy (1 paper, 2019). "The deficiency of clock genes, such as brain and muscle aryl hydrocarbon receptor nuclear translocator-like protein-1 (Bmal1), Clock, and period 2 (Per2), showed impacts on the development of cardiac hypertrophy and fibrosis, as well as cardiac dysfunction." (PMID 31597354, 2019).
Cerebral ischemia (1 paper, 2021). Restriction of arterial blood supply to the brain associated with insufficient oxygenation to support the metabolic requirements of the tissue. "Furthermore, sustained suppression of CSF Per2 expression one week after SAH was associated with higher incidence of delayed cerebral ischemia." (PMID 33562664, 2021).
circadian sleep disorders (1 paper, 2016). "For example, associations between particular mutations in the clock components CKδ, PER3 and PER2 with circadian sleep disorders have been made, and SNPs in the core clock genes PER2, CRY1, REV-ERBα and CLOCK have been associated with metabolic disturbances." (PMID 26977390, 2016).
Cirrhosis (1 paper, 2013). A chronic disorder of the liver in which liver tissue becomes scarred and is partially replaced by regenerative nodules and fibrotic tissue resulting in loss of liver function. "In particular, 37% of nuclei of hepatocytes in hepatitis showed immunopositivity for PER2, while only 7% of nuclei of hepatocytes in cirrhosis and 3% of nuclei of hepatocytes in normal liver were immunopositive." (PMID 23593233, 2013). "In cirrhosis, PER2 Immunopositivity was also observed in the cytoplasm of hepatocytes." (PMID 23593233, 2013).
Cluster headache (1 paper, 2025). A type of headache characterized by repeated attacks of unilateral pain lasting 15 to 180 minutes and associated with local autonomic signs. "Lithium,indicated as a prophylactic treatment for cluster headache has been found to significantly increase the expression of Per2 and Cry1, and reduce the expression of Per3, Cry2, and Bmal1." (PMID 39560176, 2025).
colon adenocarcinoma (1 paper, 2021). "Compared to normal skin, patients with skin cutaneous melanoma (SKCM) present significant down-regulation in the expression of BMAL1, CRY1, CRY2, PER1, PER2, and PER3, and higher expression of CLOCK, a similar pattern was also observed in patients with colon adenocarcinoma (COAD)." (PMID 34966277, 2021).
colorectal adenocarcinoma (1 paper, 2014). The most common type of colorectal carcinoma. "Moreover, in this tissue culture model, the circadian patterns of Per2 gene expression over 48 hours were more robust as compared with serum-shocked intestinal epithelial cell lines from mice (mouse small intestine epithelial cells) and humans (Caco-2 colorectal adenocarcinoma cells)." (PMID 24997189, 2014). "We hypothesized that rhythmicity of a key circadian component, PERIOD2 (PER2), would diminish along a continuum from ex vivo intestinal organoids (epithelial ‘miniguts’), nontransformed mouse small intestinal epithelial (MSIE) cells and transformed human colorectal adenocarcinoma (Caco-2) cells." (PMID 24997189, 2014). "We hypothesized that rhythmicity of PER2 would diminish in amplitude along a continuum from mouse small intestinal explants, intestinal organoids, a nontransformed mouse small intestinal epithelial (MSIE) cell line and transformed human colorectal adenocarcinoma cells (Caco-2)." (PMID 24997189, 2014).
dental fluorosis (1 paper, 2023). A condition that results from excessive fluoride ingestion during tooth development, resulting in tooth discoloration ranging from white streaks to brown stains and cracks or pits in the tooth enamel. "PER2 is also associated with orthodontic tooth movement, and enamel defects caused by dental fluorosis." (PMID 38084142, 2023).
dermatitis (1 paper, 2020). An inflammatory process affecting the skin. "Per2 is also related to inflammation response, like myocardial inflammation and dermatitis." (PMID 32426819, 2020).
developmental delay (1 paper, 2025). "Deeper vascular layer develops before the intermediate layer; thus, reduced vessel density in the Per2; CKO retina is not due to a developmental delay but is more likely due to a specific role of Per2 in the growth of the deeper vascular layer." (PMID 41240167, 2025).
esophageal tumors (1 paper, 2021). "In endometrial endometrioid carcinoma, PER2 is up-regulated nearly 15-fold in isolated esophageal tumors (Eca) with metastasis." (PMID 34966277, 2021). "However, in esophageal tumors, CLOCK, PER1, PER2, PER3, CRY1 as well as CRY2 levels are down-regulated and their downstream proteins accordingly become disordered." (PMID 34966277, 2021).
fibrosis (1 paper, 2023). the formation of excess fibrous connective tissue in an organ or tissue in a reparative or reactive process. "Independent research has reported diurnal variation in Per2 expression with low Per2 expression protecting mice from liver injury in response to high-dose acetaminophen treatment; however, low Per2 exacerbated cholestatic liver damage as well as fibrosis." (PMID 36674967, 2023).
gestational hypertension (1 paper, 2025). "Animal models with disrupted circadian clock genes—such as Bmal1 or Per2—exhibit impaired nocturnal BP regulation, heightened sympathetic tone, and increased vascular stiffness, all of which mimic features observed in gestational hypertension." (PMID 40649890, 2025).
glaucoma (1 paper, 2026). Increased pressure in the eyeball due to obstruction of the outflow of aqueous humor. "Glaucoma-induced phase shifts and amplitude alterations in the rhythmic expression of Per1, Per2, Nr1d1, and Bmal1 in the pituitary and adrenal gland, resulted in a temporal misalignment between the pituitary and adrenal rhythms." (PMID 42029480, 2026).
Glucose intolerance (1 paper, 2019). Glucose intolerance (GI) can be defined as dysglycemia that comprises both prediabetes and diabetes. "Moreover, induction of Per2 by glucocorticoids was demonstrated to affect glucose metabolism in mice with hyperglycemic conditions which are protected from glucose intolerance as lose of glucocorticoid response element in the Per2 promoter." (PMID 30642126, 2019).
Hypercholesterolemia (1 paper, 2017). An increased concentration of cholesterol in the blood.
Hyperglycemia (1 paper, 2023). An increased concentration of glucose in the blood. "Humans with variants and polymorphisms of cryptochrome 2 (CRY2) and period circadian regulator 2 (PER2), which are key circadian rhythm genes, exhibit hyperglycemia." (PMID 37960204, 2023).
hyperhomocysteinemia (1 paper, 2022). A serious metabolic condition caused by mutations in the MTHFR gene, medications, or nutritional deficiency. "Interestingly, the folate deficiency which leads to hyperhomocysteinemia, coordinately dampens PER2 and vasopressin circadian rhythms and reduces responsiveness to photic resetting of the liver clock in mice." (PMID 36465174, 2022).
hyperlipidemia (1 paper, 2017).
hypertriglyceridemia (1 paper, 2024). A laboratory test result indicating elevated triglyceride concentration in the blood.
Hypoglycemia (1 paper, 2021). A decreased concentration of glucose in the blood. "PER2 does not regulate glucocorticoid secretion towards major stressors, such as hypoglycemia, ACTH, and physical restraint, neither does PER2 regulate ACTH peptide rhythm in the hypothalamus." (PMID 34557221, 2021).
hypogonadism (1 paper, 2025). A disorder characterized by decreased function of the gonads. "Overall, these data identify Per1 and Per2 as novel atrophy-inducing genes with direct implications for their roles in regulating limb muscle mass loss during hypogonadism." (PMID 40632504, 2025).
hypothyroidism (1 paper, 2021). Abnormally low levels of thyroid hormone. "In particular, hypothyroidism has been shown to disrupt the circadian expression pattern of brain and muscle Arnt-like protein-1 (BMAL1) and of period circadian regulator 2 (Per2) and to decrease the mesor of nuclear receptor subfamily 1 (Nr1d1) and of thyrotropic embryonic factor (TEF)." (PMID 34068480, 2021).
idiopathic hypersomnia (1 paper, 2021). Idiopathic hypersomnia is a sleep disorder classified in two forms: idiopathic hypersomnia with long sleep time and idiopathic hypersomnia without long sleep time. "Here, we report parthenogenetic mosaicism mediated by second polar body retention and an unmasked PER2 (period circadian regulator 2) variant in a female with SRS and idiopathic hypersomnia (IH)." (PMID 33827678, 2021).
Infertility (1 paper, 2020). "The fertility of young Per1 and Per2 knockout mice does not differ from wild-type mice during mild-age, highlighting that Per1-Per2 absence impairs infertility only in aged mice." (PMID 32486326, 2020).
intracranial hemorrhage (1 paper, 2021). Bleeding within the SKULL, including hemorrhages in the brain and the three membranes of MENINGES. "Nonetheless, both suppression of Per2 expression in the CSF and upregulation in blood leukocytes indicate a disruption of circadian rhythm gene expression after SAH compared to control individuals without intracranial hemorrhage." (PMID 33562664, 2021).
kidney cancer (1 paper, 2021). Primary or metastatic malignant neoplasm involving the kidney. "Five rhythmic genes, including PER2, DBP, PER3, CRY2, and RORA, have significant prognostic role in patient survival in at least two types of kidney cancer." (PMID 34977153, 2021).
lupus nephritis (1 paper, 2021). Glomerulonephritis in the context of systemic lupus erythematosus. "We found modest disruption of renal diurnal rhythm of Rev-erbα and marked dysregulation of both Per1 and Per2 in the nephritic kidneys suggesting that these could be potential targets for circadian modulating therapy in lupus nephritis." (PMID 34488619, 2021).
metastatic melanoma (1 paper, 2018). A melanoma that has spread from its primary site to another anatomic site. "In metastatic melanomas, male presented increased percentage of tumor showing high expression of NRD1, PER2, and PER3 (P = 0.015, P = 0.028, and P < 0.001, respectively)." (PMID 29946530, 2018).
muscle atrophy (1 paper, 2022). The loss of muscle tissue due to inactivity or disease. "In line, PER2 is upregulated in mouse models of spinal muscular atrophy and denervation-induced muscle atrophy whereas siRNA-mediated downregulation of PER2 enhances protein synthesis and suppresses autophagy in skeletal muscle." (PMID 35547572, 2022).
myopia (1 paper, 2024). "Retinal genes in the OcclVopen*time interaction category in myopia progression include the circadian clock genes PER2 and ARNTL and PCSK1, whose product processes prohormone and neuropeptide precursors." (PMID 39028695, 2024).
paroxysmal AF (1 paper, 2021). "The expression of BMAL1, CRY2, NR1D2, PER2, and RORA was significantly lower in patients with persistent AF than in those with paroxysmal AF (persistent AF vs. paroxysmal AF, all p < 0.05)." (PMID 33430447, 2021).
pituitary tumor (1 paper, 2023). A benign or malignant neoplasm affecting the pituitary gland. "Diurnal rhythm of PER2 parallels those of cell cycle genes (Ccnb2, Cdc20 and Espl1) in pituitary tumors, supporting PER2 as a driver of rhythmicity in these cell cycle genes and implicating a diurnal rhythm in cell cycle." (PMID 37215573, 2023). "Taken together, Per2 ablation has an inhibitory effect on pituitary tumorigenesis, implicating PER2 as a pituitary tumor-promoting factor." (PMID 37215573, 2023). "Whether immune cell infiltration has a role in PER2 regulation of pituitary tumors requires further investigations." (PMID 37215573, 2023). "However, the mechanisms by which the clock genes such as Per2 are disrupted in pituitary tumors remains unresolved." (PMID 37215573, 2023). "However, it remains to be determined whether epigenetic modifications are involved in PER2 regulation of pituitary tumors." (PMID 37215573, 2023).
polycystic ovarian syndrome (1 paper, 2023). "In addition, the ovaries of a mouse model of polycystic ovarian syndrome (PCOS) were shown to have an anomaly for the time of Per2 rhythm." (PMID 36675058, 2023).
premature ovarian failure (1 paper, 2022). "The Per2 gene modulates the circadian rhythms that influence biological processes and female Per1/Per2 mutants show premature ovarian failure and impaired ovarian function." (PMID 35806403, 2022).
pulmonary fibrosis (1 paper, 2023). Chronic progressive interstitial lung disorder characterized by the replacement of the lung tissue by connective tissue, leading to progressive dyspnea, respiratory failure, or right heart failure. "It has been described that the circadian clock regulates the activation of the NRF2/glutathione-mediated antioxidant pathway to modulate pulmonary fibrosis, and the expression of PER2 (a clock protein) in bronchiolar epithelial cells is responsive to glucocorticoids." (PMID 36985953, 2023).
Rectal prolapse (1 paper, 2023). Protrusion of the rectal mucous membrane through the anus. "Together, these results reveal that a deficiency in Per2 leads to intense inflammation in the rectum prior to rectal prolapse." (PMID 37660913, 2023). "Our findings revealed that mice deficient in Per2 spontaneously developed rectal prolapse, which was accompanied by inflammatory bowel disease and gut microbiota disorders." (PMID 37660913, 2023). "We report that Per2 deficiency in mice increased susceptibility to intestinal inflammation and resulted in spontaneous rectal prolapse." (PMID 37660913, 2023). "Our results suggest that PER2 is essential to the capacity of pathogen clearance in macrophages and that Per2-deficient mice represent a potential animal model of rectal prolapse." (PMID 37660913, 2023). "MUC2 expression in the colon of Per2−/− mice did not change compared to WT mice, and colon inflammation only occurred when Per2−/− mice developed rectal prolapse." (PMID 37660913, 2023). "In this study, we investigate the role of the rhythmic gene Period2 (Per2) in triggering inflammation in the rectum and its contribution to the pathogenesis of rectal prolapse." (PMID 37660913, 2023). "In this study, we investigated the potential role of circadian Period2 (Per2) in rectal prolapse." (PMID 37660913, 2023). "In order to determine the major factor responsible for inducing rectal prolapse in Per2−/− mice, we enriched rectal lamina propria (LP) lymphocytes from the rectal mucosa of 16-week-old WT mice, nonprolapsed and prolapsed Per2−/− mice, and analyzed the types of infiltrating cells." (PMID 37660913, 2023). "In this study, we found that Per2-null mice had a decreased capacity for pathogen clearance, resulting in a progressive disturbance of the gut microbiome that eventually led to the natural occurrence of rectal prolapse." (PMID 37660913, 2023). "The number of goblet cells did not decrease and more mucous proteins were expressed in the rectal prolapse of Per2−/− mice, suggesting that the rectal prolapse in Per2−/− mice was not caused by impaired intestinal mucosal function." (PMID 37660913, 2023). "Taken together, our findings identify a novel role for Per2 in regulating the capacity of pathogen clearance in macrophages and gut inflammation and suggest a potential animal model that more closely resembles human rectal prolapse." (PMID 37660913, 2023). "The expression of Muc2 and goblet cell differentiation factor Gfi1 in the rectum of Per2−/− mice was also higher than that of WT mice, suggesting that the occurrence of rectal prolapse in Per2−/− mice is not related to impairment of intestinal mucosal immunity." (PMID 37660913, 2023).
renal cell carcinoma (1 paper, 2014). "Among these genes, Per2 is reported to have tumor suppressor properties, but little is known about the correlation between Per2 and HIF, which is the main target of renal cell carcinoma (RCC) therapy." (PMID 25333958, 2014).
septic shock (1 paper, 2021). Shock caused by infection; frequently caused by gram negative bacteria, although some cases have been caused by other bacteria, viruses, fungi, and protozoa; characterized by fever, chills, tachycardia, tachypnea, and hypotension. "While CRY1, NR1D1, NR1D2, DBP, PER2 were suppressed in septic shock patients, CRY2, surprisingly was significantly upregulated compared to healthy young men." (PMID 33900485, 2021). "In addition, the expression of the clock genes CRY1, NR1D1, NR1D2, DBP, and PER2 were suppressed in septic shock patients, whereas CRY2 was significantly upregulated compared to healthy young men." (PMID 33900485, 2021).
Shock (1 paper, 2021). The state in which profound and widespread reduction of effective tissue perfusion leads first to reversible, and then if prolonged, to irreversible cellular injury. "Additionally, we found that NR1D1, NR1D2, CRY1, CRY2, PER1, PER2 and DBP had altered rhythms in at least some patients with septic shock." (PMID 33900485, 2021).
skin cancer (1 paper, 2014). "Downregulation of Per2 is in line with previous reports for colorectal and skin cancer indicating that Per2 deregulation is correlated with malignant transformation in different systems." (PMID 24875049, 2014).
Smith-Magenis syndrome (1 paper, 2015). Smith-Magenis syndrome (SMS) is a complex genetic disorder characterized by variable intellectual deficit, sleep disturbance, craniofacial and skeletal anomalies, psychiatric disorders, and speech and motor delay. "In children with Smith-Magenis syndrome, a genetic disorder associated with skeletal malformations, the Per2 gene is also expressed with high variability and no Per2 rhythm." (PMID 26580614, 2015).